SV2A (synaptic vesicle glycoprotein 2A)
Description:
Plays a role in the control of regulated secretion in neural and endocrine cells, enhancing selectively low-frequency neurotransmission. Positively regulates vesicle fusion by maintaining the readily releasable pool of secretory vesicles (By similarity). (Microbial infection) Receptor for the C.botulinum neurotoxin type A2 (BoNT/A, botA); glycosylation is not essential but enhances the interaction. Probably also serves as a receptor for the closely related C.botulinum neurotoxin type A1.
Synonyms: KIAA0736; SV2; SLC22B1; DEE113
Tractability: Small molecule: an approved drug acts on it; a structure with a bound ligand is known; it belongs to a druggable protein family. Antibody: its Gene Ontology location is reachable by antibodies, with high confidence; UniProt predicts a signal peptide or a membrane-spanning region. PROTAC: ubiquitination databases record sites on it; its protein half-life has been measured.
Target class: Vesicular neurotransmitter transporter family; Transporter; Electrochemical transporter
Chemical probes: BRIVARACETAM (high quality)
Gene: Protein-coding gene on chromosome 1 (149,903,318 to 149,918,572, reverse strand). Ensembl gene ENSG00000159164.
Subcellular location: Presynapse; Cytoplasmic vesicle, secretory vesicle, synaptic vesicle membrane
Subcellular location (Human Protein Atlas): Cytosol
Pathways (Reactome):
Disease: Toxicity of botulinum toxin type A (botA); Toxicity of botulinum toxin type D (botD); Toxicity of botulinum toxin type E (botE); Toxicity of botulinum toxin type F (botF)
Gene Ontology:
Molecular function: protein kinase binding; transmembrane transporter activity
Biological process: synaptic vesicle priming; chemical synaptic transmission; transmembrane transport
Cellular component: endoplasmic reticulum; neuron projection; plasma membrane; synaptic vesicle; synaptic vesicle membrane; cell-cell junction; GABA-ergic synapse; glutamatergic synapse; membrane; neuromuscular junction; presynapse; presynaptic active zone
Genetic constraint (gnomAD): Loss-of-function variants: 25 observed, 81.3 expected, observed/expected ratio (o/e) 0.31, 90% interval 0.22 to 0.43. The upper end of that interval is the gene's LOEUF score, 0.43, which puts it in group 1 of 6, group 1 being the genes least tolerant of losing a copy. Missense variants: 752 observed, 1,016.7 expected, observed/expected ratio (o/e) 0.74, 90% interval 0.7 to 0.79. Synonymous variants: 355 observed, 404.12 expected, observed/expected ratio (o/e) 0.88, 90% interval 0.81 to 0.96.
Homologues: Orthologues: chimpanzee SV2A (99% identical), macaque SV2A (99% identical), pig SV2A (99% identical), mouse Sv2a (99% identical), rabbit SV2A (99% identical), dog SV2A (98% identical), rat Sv2a (98% identical), guinea pig SV2A (98% identical), tropical clawed frog sv2a (82% identical), zebrafish sv2a (79% identical). Paralogues in human: SV2C (63% identical), SV2B (59% identical).
Diseases named in the same sentence as SV2A in open-access papers:
SV2A is named in the same sentence as 81 diseases in open-access papers, as found by Europe PMC text mining. Sharing a sentence is not in itself a finding about the gene and the disease. The quoted sentences say what the papers report.
epilepsy (65 papers, 2011 to 2026). A brain disorder characterized by episodes of abnormally increased neuronal discharge resulting in transient episodes of sensory or motor neurological dysfunction, or psychic dysfunction. "Loss of function mutations in the human SV2A gene result in intractable epilepsy, however the mechanism underpinning this is still unclear." (PMID 39853744, 2025). "The first human SV2A mutation linked to epilepsy was reported in 2015, in an individual with intractable epilepsy." (PMID 39853744, 2025). "Synaptic vesicle protein 2A (SV2A) is a synaptic vesicle (SV) protein implicated in epilepsy, with a debated physiological role." (PMID 39853744, 2025). "Further evidence of a potential link between SV2A loss of function, dysregulated Syt1 trafficking and epilepsy comes from the only human SV2A missense mutation to be investigated in detail (R383Q)." (PMID 39853744, 2025). "Several studies in rodent epilepsy and dysplastic cortex models report loss of synaptic vesicle glycoprotein 2A (SV2A), indicating synapse reduction and altered neurotransmission." (PMID 41366489, 2025). "Through fine mapping and other molecular approaches, the authors identified the SV2A gene as associated with the epilepsy trait." (PMID 39157583, 2024). "This discovery not only provides insight into the mechanism of action of levetiracetam but also implies the diagnostic and therapeutic potential of targeting SV2A in the management of epilepsy and related disorders." (PMID 38884834, 2024). "As a unique target for treating epilepsy, molecular‐level alterations of SV2A have been predicted to affect susceptibility to pharmacoresistance." (PMID 38801174, 2024). "In literature, several studies on animal models showed how SV2A missense mutations cause an imbalance in GABAergic and glutamatergic transmission, leading to epilepsy." (PMID 35350397, 2022). "Clinical studies in patients with epilepsy or dementia syndromes have shown that SV2A tracers can reliably detect a loss of synaptic density, which is associated with neuronal damage." (PMID 35411002, 2022). "Studies in animal models demonstrated that SV2A loss-of-function caused premature mortality and severe epilepsy." (PMID 35686059, 2022). "Many of the DEGs were involved in synapses, ion channels, neurons, and ECM, demonstrating that our sv2a loss-of-function zebrafish model mimics aspects of human epilepsy." (PMID 35686059, 2022). "Synaptic vesicle glycoproteins 2A (SV2A) are involved in neurotransmitter transportation in the CNS and have been linked to several neuronal disorders, such as epilepsy, schizophrenia, Alzheimer’s disease, and Parkinson’s disease." (PMID 35008899, 2021). "The antiepileptic drug levetiracetam (Keppra®) binds to SV2A, suggesting a role for SV2A in the pathology underlying certain forms of epilepsy." (PMID 31052478, 2019). "Adding further credence to a direct role for SV2A in epilepsy pathogenesis is the recent identification of a homozygous mutation (R383Q) in a highly conserved residue of SV2A in an individual with intractable epilepsy, developmental and growth delay." (PMID 26903854, 2016). "In this context, the classic knockout approach cannot be used to precisely characterise the role of SV2A, even if, once again, this protein can be linked to epilepsy." (PMID 27861538, 2016). "SV2A also serves as a specific binding site for certain antiepileptics and is implicated in the treatment of epilepsy." (PMID 27265781, 2016). "Synaptic vesicle protein 2A (SV2A) is an integral membrane protein necessary for the proper function of the central nervous system and is associated to the physiopathology of epilepsy." (PMID 25914622, 2015). "The next step is to apply this methodology in newly diagnosed patients with epilepsy from the BrainDrugs-Epilepsy cohort study and investigate how SV2A-LEV target engagement is associated with LEV treatment efficacy, including seizure freedom and side effects during follow-up." (PMID 38758370, 2024).
epilepsy (continued). "In humans, only three variants have been reported to link SV2A to epilepsy." (PMID 35686059, 2022). "The proteins SV2A and SV2B regulate presynaptic Ca2+ accumulation, action potential-dependent neurotransmitter release in e.g., hippocampal neurons and their absence induces epilepsy e.g., SV2A deficiency showed elevated seizure vulnerability in an SV2A knockout model of zebrafish." (PMID 36406753, 2022). "Observations from a rat model of epilepsy and dysplastic cortical tissue suggested that the loss of synaptic vesicle glycoprotein 2A (SV2A) may lead to alterations in neurotransmission." (PMID 34978594, 2022). "This study analyzed SV2A expression in the hippocampus of C, C+LEV, EPI, and EPI+LEV rats, in order to determine if alterations in SV2A protein expression associated to epilepsy may be important for LEV effectiveness." (PMID 33922424, 2021). "In view of the fact that synaptic loss is the pathology of both epilepsy and AD, this review summarizes the potential role of SV2A in the pathogenesis of AD, and suggests that SV2A should be used as an important target molecule of PET imaging agent for the early diagnosis of AD." (PMID 34795573, 2021). "As previously stated, the SV2A isoform is associated with the physiopathology of epilepsy." (PMID 31052478, 2019). "The lower levels of SV2A in both models could corroborate the hypothesis that SV2A reduction is implicated in epilepsy progression and/or maintenance." (PMID 28588450, 2017). "Indeed, a recent study showed that a missense mutation R383Q in the SV2A gene caused intractable epilepsy and involuntary movements, which were accompanied by developmental retardation." (PMID 27471467, 2016). "However, the mechanism via which SV2A loss translates into epilepsy and pharmacoresistance remains unclear." (PMID 38801174, 2024). "Mice with a genetic ablation of both SV2A/B and stonin-2 display a worse seizure phenotype, and more prominent lethality than SV2A/B knockout mice alone suggesting stonin-2 dysfunction may increase susceptibility to epilepsy." (PMID 26903854, 2016). "Collectively, these insights support the notion that SV2A plays a significant role in both the pathogenesis and treatment of epilepsy, making it a promising target for future therapeutic interventions." (PMID 39865817, 2025). "For example, SV2A levels are significantly lower in humans with multiple forms of epilepsy and in a series of preclinical epilepsy models." (PMID 39853744, 2025). "The potential for SV2A‐dependent epilepsy to be a result of dysfunctional Syt1 expression and localisation is also discussed." (PMID 39853744, 2025). "There were 771 out of 5648 DEGs that were successfully converted into human orthologs and significantly enriched in neuropsychiatric disorders (e.g., epilepsy and anxiety), including synaptic vesicle glycoprotein 2A (sv2a) and synapse proteins (e.g., syt1)." (PMID 39083243, 2025). "PET studies of SV2A in the rat brain have shown differences in several brain regions in a model of epilepsy, Parkinson’s and Huntington’s disease." (PMID 40533661, 2025). "Recently, the role of SV2A in the pathogenesis and treatment of epilepsy has gained significant attention due to compelling evidence." (PMID 39865817, 2025). "The role that SV2A performs in presynaptic physiology and how its dysfunction links to epilepsy continues to be a matter of debate." (PMID 39853744, 2025). "Studies have revealed that SV2A has a crucial role in regulating neurotransmission and is vital in seizures and epilepsy development." (PMID 38884834, 2024). "The expression of SV2A in epilepsy displays a complex and variable pattern during the progression of the pathology." (PMID 35573314, 2022). "Although several rodent knockout models have demonstrated the importance of SV2A for functional neurotransmission, its precise physiological function and role in epilepsy pathophysiology remains to be elucidated." (PMID 35686059, 2022).
epilepsy (continued). "Lower SV2A in epileptic lesions has been repeatedly observed in brain tissue slices from animal models of epilepsy and epileptic patients." (PMID 34978594, 2022). "The discovery of the relationship between SV2A and epilepsy triggered the development of the first SV2A radiotracer, [3H]ucb 30889, with the aim to identify levetiracetam’s binding sites in the rat brain and spinal cord." (PMID 35401097, 2022). "Synaptic vesicle glycoprotein 2A (SV2A) binding has been shown to be reduced in brain removed in epilepsy surgery." (PMID 34812749, 2022). "Synaptic vesicle glycoprotein 2A (SV2A) binding is reduced in brain specimen obtained by epilepsy surgery." (PMID 35359649, 2022). "Compared to the other genetic epilepsy models, sv2a–/– zebrafish displayed a considerably greater number of DEGs." (PMID 35686059, 2022). "Epilepsy demonstrates the intricate dynamics of SV2A expression, since it derives from a disruption of the excitation-inhibition balance in which SV2A seems to play a role." (PMID 35573314, 2022). "In the current study, we explored the role of SV2A in the brain development and pathophysiology of epilepsy using an in vivo zebrafish model." (PMID 35686059, 2022). "[11C]UCB-J, a SV2A PET radioligand, has been used to explore SV2A differences in clinical populations including epilepsy, depression, and Alzheimer’s disease." (PMID 35503134, 2022). "At recombinant SV2 proteins, padsevonil’s affinity for SV2A was greater than that of levetiracetam or brivaracetam, another SV2A ligand that has been approved for epilepsy therapy." (PMID 34776956, 2021). "In some animal models of epilepsy, SV2A levels are decreased in the hippocampus; which is particularly epileptogenic, making it the main altered anatomical substrate of TLE." (PMID 33922424, 2021). "The mRNA levels of SV2A were found to be significantly elevated in the PF-treated rats when compared with those of the control rats with epilepsy." (PMID 34805114, 2021). "In different stages of epilepsy, SV2A is co-expressed generally with GABAergic markers, suggesting a preferential expression of SV2A by GABAergic interneurons." (PMID 33922424, 2021). "The isoforms SV2A, SV2B and SV2C are implicated in neurological diseases such as epilepsy, Alzheimer's and Parkinson's disease." (PMID 33588752, 2021). "This is relevant since several reports have shown preferential SV2A function on GABAergic neurotransmission, even during epilepsy." (PMID 33922424, 2021). "Furthermore, SV2A rs626785 produces differentially expressed splice variants in human amygdala (GTEx Analysis Release V8, dbGaP Accession phs000424.v8.p2, sQTL), suggesting additional gene regulatory processes linking anxiety and amygdala gene expression, and possibly epilepsy." (PMID 32839459, 2020). "The emergence and now widespread use of effective anti-epilepsy medications, such as Brivaracetam, which modulate the function of the synaptic vesicle glycoprotein 2A (SV2A) protein, identified this protein as an interesting target." (PMID 31541283, 2020). "Different studies have explored the role of the SV2A protein in epilepsy: in humans, several epileptic disorders are related with a reduction in the amount of SV2A, suggesting a role of this protein in the epileptogenesis and/or the ictiogenesis." (PMID 31166988, 2019). "Of note, SV2A-targeting drugs have been shown to preferentially disrupt GABAergic neurotransmission in epilepsy studies." (PMID 31866830, 2019). "The most prominent epilepsy-related member, SV2A, is the main target through which levetiracetam and brivaracetam exert their antiepileptic and possibly antiepileptogenic effects." (PMID 31887157, 2019). "The SV2A isoform is the most studied and its implication in epilepsy therapy led to the development of the first SV2A PET radiotracer [18F]UCB-H." (PMID 31052478, 2019).
epilepsy (continued). "Thanks to the availability of resected tissues from human brains after surgical treatments for pharmacologically-resistant epilepsies, several teams had the opportunity to analyze SV2A expression in such conditions." (PMID 28588450, 2017). "All these observations highlight a potential neuroprotective role for SV2A, as its absence appears to facilitate the progression of epilepsy." (PMID 28588450, 2017). "At present, our understanding of the normal function of SV2A and its possible involvement in diseases like epilepsy is limited." (PMID 27861538, 2016). "With this study, we sought to develop a relevant model enabling analysis of SV2A’s role in the occurrence or progression of epilepsy." (PMID 27861538, 2016). "In order for us to be able to investigate the possible role of the SV2A protein in epilepsy, we first studied a conditional mouse line carrying SV2A deletion in the hippocampus (i. e., Grik4:SV2A-cKO)." (PMID 27861538, 2016). "In this regard, a protein involved in synaptic vesicle dynamic, SV2A, has been recently found to be an effective target for epilepsy supporting the presynapse as a target to control hyperexcitability." (PMID 25520655, 2014). "Yet, the only example of a vesicular protein as a target for the treatment of epilepsy is the synaptic vesicle protein 2A (SV2A), the binding site of levetiracetam (LEV)." (PMID 24009559, 2013). "As outlined for SV2A, results from transgenic mice, distinct acute and chronic rodent epilepsy models and resected human epileptic tissue are crucial to constitute a clear and complete conception of new, potential AED targets." (PMID 24009559, 2013). "We analyzed several regions in the central nervous system, focusing the analysis of the SV2 protein expression in telencephalic regions given the relationships of SV2A with epilepsy." (PMID 23937191, 2013). "This putative role of levetiracetam is also sustained by the observation that brivaracetam, a compound which binds SV2A with a higher affinity than levetiracetam, exhibits more potent anticonvulsant properties in various acute epilepsy models." (PMID 23937191, 2013). "Brain SV2A levels are decreased in autopsy tissue of epilepsy patients, and could be more diminished in EAD than in NEAD." (PMID 39949405, 2025). "A link to human epilepsy as a result of SV2A dysfunction has been assumed for at least two decades, since the leading anti‐seizure medication, levetiracetam, was found to bind SV2A." (PMID 39853744, 2025). "Disruption of SV2A leads to Syt1 mislocalization and impaired neurotransmission, a mechanism that may contribute to epilepsy." (PMID 40430045, 2025). "Intriguingly, there are potential links between SV2A dysfunction, epilepsy and Syt1." (PMID 39853744, 2025). "A key downstream consequence of SV2A dysfunction in rodents is epilepsy." (PMID 39853744, 2025). "The expression and distribution of SV2A during different stages of epilepsy are important for revealing the antiepileptic mechanism of LEV and the patterns of the occurrence and development of epilepsy, providing significant guidance for the clinical treatment and prevention of epilepsy." (PMID 37845841, 2023). "It has been proposed that the molecular mechanism underlying the therapeutic effects of LEV is based on its specific binding to the synaptic vesicle protein 2 isoform A (SV2A) to inhibit the abnormal discharge of the epilepsy circuit, ultimately preventing the occurrence of seizures." (PMID 37845841, 2023). "Frontline treatment for epilepsy is based on small molecule drugs that target ion channels and neurotransmitter systems, including levetiracetam and other synaptic vesicle glycoprotein 2A (SV2A)-modulating compounds." (PMID 38259288, 2023). "Finally, we reported that SV2A expression seems to be regulated in a complicated way, with very dynamic changes in time and space during the progression of epilepsy." (PMID 35573314, 2022).